CD4 (CD4 molecule)
Diseases named in the same sentence as CD4 in open-access papers (continued):
Sharing a sentence is not in itself a finding about the gene and the disease.
tumor (continued). "Reportedly, the Forkhead box O (FOXOs) family intrinsically influences the anti-tumour immune response and the infiltration levels of immune cells, including CD4+ T cells and CD8+ T cells, B cells, neutrophil cells, macrophage cells, and dendritic cells." (PMID 32181755, 2020). "Several clinical trials have been completed and/or are currently ongoing to enhance tumor-specific responses through neoantigen vaccination to induce expansion of neoantigen-specific CD4+ and CD8+ T cells." (PMID 32117226, 2020). "RNA sequencing (RNA-seq) analyses of Yap-deleted tumor-infiltrating lymphocytes (TILs) revealed up-regulation of key signals important for CD4+ and CD8+ T-cell activation, differentiation, and function." (PMID 31929526, 2020). "The key players in this response are APCs, among which macrophages, DC and B cells, which are able to present tumor antigen to CD4+ helper T cells." (PMID 32226771, 2020). "The treatment also increases tumor-infiltrating IFNγ-producing CD4+ and CD8+ T cells and inhibits tumor growth in vivo." (PMID 33086676, 2020). "Clinical trials have demonstrated that ACT and tumor infiltration by Th1 CD4+ T cells can mediate regression of advanced solid tumors." (PMID 33362774, 2020). "Regulatory CD4+ T cell derived IL-10 facilitated tumor progression through inhibiting the recruitment or differentiation of inflammatory monocytes in skin." (PMID 33343560, 2020). "There were lower tumor purity (P = 4.75e-16) and higher percent of tumor-infiltrating immune cells (B cell P = 1.48e-05, T cell CD4 P = 8.26e-4, Neutrophil P = 3.58e-06, and macrophage P = 7.14e-10) in C1 than C2." (PMID 33584801, 2020). "A similar mechanism is found in the tumour microenvironment in which metabolically active tumour cells deplete nutrients and can significantly lower glucose availability, thereby inhibiting CD4+ Th1 and CD8+ effector T cell function." (PMID 33202938, 2020). "MDSCs are recruited from peripheral lymphoid organs to tumour sites, promoting the production of CD4+Foxp3+Tregs." (PMID 33308251, 2020). "Previous study revealed that tumor-infiltrating naive CD4 T cells are the important source of tumor-infiltrating regulatory T cells, which suppress the antitumor function of effector T cells and NK cells." (PMID 32793475, 2020). "TRIM28 levels had strong negative associations with the infiltrating levels of CD8+ T cells in 24 tumor types, CD4+ T cells in 14 tumor types, macrophages in 25 tumor types, neutrophils in 27 tumor types and dendritic cells in 24 tumor types." (PMID 33091876, 2020). "miRNAs are also involved in the regulation of immune cells within the tumor microenvironment, including cytotoxic, CD4 or γδ T lymphocytes, natural killer (NK), macrophages and myeloid-derived suppressor cells (MDSCs)." (PMID 32604720, 2020). "In a breast cancer mouse model, CXCR2+ MDSCs promoted tumor growth and metastasis by secretion of IL-6 and modulation of CD4+ and CD8+ T cell recruitment to the tumor site." (PMID 32509781, 2020). "In a similar, but purely OPSCC and T cell focused transcriptome study, highly active tumor resident and tumor-reactive populations of CD4+ and CD8+ T cells that displayed actionable checkpoints were found in OPSCC." (PMID 33425717, 2020). "We observed a numerical decrease of CD4+ T cells, which inhibit pro-tumor regulatory T cells as well as anti-tumor natural killer cells." (PMID 32737655, 2020). "The results presented above indicate that CD4+ T cell infiltration correlated with ACAA1, and most subsets of CD4+ cells were reduced in the tumor stroma." (PMID 33194642, 2020). "It has been shown in different murine tumor models that TNF-α secreted by CD4+ T cells, and partially by CD8+ T cells, induces myelopoiesis, which increases the frequency of MDSCs." (PMID 32793192, 2020).
tumor (continued). "Previous studies have shown that high infiltration of M1 and CD4 T cells, E0 expression, mast cell expression, and low Treg expression or other states are the best state of hot tumours, which can increase the efficacy of immunotherapy." (PMID 32723333, 2020). "The tumor growth ratio (TGR) was significantly higher in patients with expansion of CD4 THD burst compared to the rest of patients (median 2.67 vs. 0.86, p = 0.0049), and also when considering only progressors (median 2.67 vs. 1.03, p = 0.0126)." (PMID 32033028, 2020). "CTLA4 mAbs have been shown to enhance the anti-tumor immunity in humans by blocking activation of FOXP3+CD4+ Tregs." (PMID 32733457, 2020). "Overall, the analysis showed M2 macrophages, CD8+ T-cells and CD4+ T-cells as the most abundant hematopoietic cell population in the tumor infiltrate; in addition a moderate presence of monocytes and regulatory T-cells (Treg) was predicted." (PMID 32670260, 2020). "Preclinical data presented here support this combination of agents and show that tetratherapy increases the functionality of CD4+ and CD8+ T cells in the TME, which is associated with augmented anti-tumor efficacy relative to the triplet, doublet or singlets." (PMID 33747894, 2020). "For example, induction of CD8+ T cell-mediated anti-tumor immunity by B cell-derived sEVs is reliant on cross-talk with the T helper cell arm (CD4+ T cell) and innate cell arm (NK cells) of the immune system." (PMID 32765528, 2020). "The authors noted that A. muciniphila increases the recruitment of CCR9+CXCR3+CD4+ T lymphocytes to tumor beds in an IL-12-dependent manner." (PMID 32117295, 2020). "Here, tumor protection was still observed after depletion of circulating T cells but in the presence of functional Trm T cells, suggesting that CD4+ and CD8+ Trm T cells were responsible for protection." (PMID 33240271, 2020). "The contact of mature DCs with tumor-derived factors can induce Treg1-like cells from naive CD4+ T cells through high IL-10 and low IL-12 signaling." (PMID 33036244, 2020). "This would improve the therapeutic potency as mouse studies revealed a superior anti-tumor effect of early memory CD4+ T cells." (PMID 32504246, 2020). "In response to tumor cells, human naïve CD4 and CD8 T cells were activated and differentiate into effector T cells and memory T cells, and the latter react more rapidly than naïve T cells and provide a more robust response upon repeat stimulation." (PMID 33061819, 2020). "ENO1 showed correlation with immune infiltrates including B cells, CD8+ and CD4+ T cells, macrophages, neutrophils, and dendritic cells, and tumor purity." (PMID 33643901, 2020). "The specific lymphocyte subpopulations involved were investigated by depleting immunocompetent male and female mice with a weekly intraperitoneal injection of anti-CD4 or anti CD8 specific antibodies before injecting them with Fhit-transfected tumor cells." (PMID 32545680, 2020). "The number of CD4 + cells in distant tumours among rats in the RFA-OK-432 group was also significantly higher than that among rats in the control, RFA-only, and OK-432 groups (all P < 0.05)." (PMID 32541941, 2020). "The TIICs mainly includes B cells, T cells (CD8+ T cells, CD4+ T cells, follicular helper T cells, and Tregs), macrophages, and NK cells, which play key roles in tumor promotion and/or tumor suppression." (PMID 32095823, 2020). "In this study, CD4 naive T cells significantly decreased while Th1 cells and DC cells increased in tumor tissues." (PMID 32923385, 2020). "The different CD4+ T cell subsets have distinctive helper functions, with Th1 cells being described as the most potent to support anti-tumor immunity." (PMID 32504246, 2020). "A-SMase overexpression in these cells restores CD8+ and CD4+ T cells and DCs infiltration while reducing levels of infiltrating MDSCs and Tregs, thereby reducing tumour growth." (PMID 32858889, 2020).
tumor (continued). "For the signature of HPV− group, miR-605-5p related to unfavorable prognosis was found negatively associated with CD8+ T cells, macrophages M1, and activated memory CD4+ T cells, which acted as tumor suppressors." (PMID 33643915, 2020). "There was a trend for an increase in the number of CD4 T cells/g of tumor, but this fell just short of statistical significance (p = 0.07)." (PMID 32502202, 2020). "In return, IL-1ß drives the polarization of CD4+ T cells into Th17 cells that promote tumor angiogenesis in the TME, which hampers the antitumor response of gemcitabine and 5-fluorouracil." (PMID 32733461, 2020). "On the other hand, the ratio of CD4(+) to CD8(+) T cells does have an effect on the anti-tumor activity of CAR T cells." (PMID 33303017, 2020). "Flow cytometry was used to evaluate CD4+CD25+ spleen cell populations of the tumor-bearing mice that received WW2/WW3 protein treatment and those of the control group." (PMID 32306719, 2020). "Based on adoptive transfer of tumor-reactive CD4 T cells or CD4 T cell depletion, it was initially demonstrated that CD4 T cells are necessary for protection against tumors lacking MHC-II." (PMID 32630460, 2020). "Previous studies have improved our understanding of the functions and origins of TILs and demonstrated that tumor-infiltrating immune cells are associated with the prognosis of STAD, especially in CD4+ and CD8+ T cells." (PMID 33469515, 2020). "The proportion of CD45+CD3+CD8+ expressing T-cells and CD45+CD4+CD25+FoxP3+ expressing regulatory T-cell (Treg) cells remained unchanged in 3 × 5 Gy RT-treated tumours compared to untreated control tumours." (PMID 32641865, 2020). "This approach restored local immune responses at the tumor site by increasing the percentage of CD8+ T cells while keeping CD4+ T cells similar between AAV‐DNase I and AAV‐null treatments." (PMID 32813937, 2020). "The resulting high Treg/CD8 and Treg/CD4 ratios it has been increased also in distal tumor-draining lymph nodes (TDLN)." (PMID 32226771, 2020). "While often treated as a monotypic cell type, significant diversity of function and pathology exists for CD4+ T cells in a tumor, with numerous subsets described to predict various disease outcomes." (PMID 32244756, 2020). "Nonetheless, it is the CD4+CD25- population that changes towards reduction to make a homeostatic alteration in CD4+CD25+/CD4+ ratio as a response to increasing tumor burden." (PMID 32306719, 2020). "Generally, CD4+ T cells can be divided into two subsets, T helper 1 (Th1), and T helper 2 (Th2), which elicit antitumor effects and tumor-promoting effects, respectively." (PMID 32424240, 2020). "Our results suggest that circulating and tissue-resident ILCs have the intrinsic capacity to respond to the immediate cytokine milieu and regulate local CD4+ T-cell responses, with potential implications for anti-tumor immunity and inflammation." (PMID 32341343, 2020). "The particularly strong association of HEDDR with survival thereby supports the increasingly appreciated role of CD4+ T cells in anti-tumor immune responses." (PMID 32650450, 2020). "The MEK/ERK inhibitors exerted mild or even stimulatory effects on dendritic cells, CD4+ T cells, and tumor antigen-specific CD8+ T cells, but inhibitory effects on infiltrations of regulatory T cells and monocyte/macrophages." (PMID 32874132, 2020). "Remarkably, blockade of Gal1 with monoclonal antibodies increase CD4+ CD8+ tumor infiltrating lymphocytes in melanoma and lung cancer through T-cell proliferation and the induction of tumor-specific T1-type immunologic response in lymph nodes." (PMID 32168866, 2020). "For further verification of the expression of CD4/IFNGR2/CD68/CSF1R as immune signatures in OSA tumor microenvironment, RT-qPCR was performed using mRNA from 45 collected primary surgical tissue samples of OSA primary tumors." (PMID 32850346, 2020).
tumor (continued). "CD56dimNK cells in the tumor area of HCC patients expressed fewer IFN-γ than non-CD56dimNK cells, which was associated with CD4+CD25+Tregs in vitro." (PMID 33614486, 2020). "In a subsequent study, the same team found that the agonist of CD40 induced heavy T cell infiltration into tumours upon combination with Gem and resulted in CD4+ and/or CD8+ T cell-dependent tumour regression." (PMID 32061257, 2020). "The inflamed phenotype comprises the concurrent presence of both CD8+ and CD4+ T cells with inhibitory cells (i.e., macrophages, fibroblasts, Treg, suppressor myeloid cells and B cells) in the tumor parenchyma." (PMID 32423420, 2020). "CD4+ Th1 cells, CD4+ CTLs, and follicular helper T cells exert potent anti-tumor activity, whereas regulatory T cells or, under certain circumstances, CD4+ Th2 cells and CD4+ Th17 cells show tumor-promoting activity." (PMID 32216826, 2020). "CD4+ T cell transfer into lymphodepleted animals or Tregs depletion promoted GzmB expression by tumour-infiltrating CD4+, an effect prevented by IL-2 neutralization." (PMID 32680511, 2020). "Both in the tumor and liver tissues, there is a decrease in the proportion of CD4+ and an increase in the proportion of DNT." (PMID 32448803, 2020). "In a mouse breast cancer model, tumor-evoked Bregs (tBregs) promoted transition of resting CD4+ T cells to Treg cells which correlated with greater metastasis." (PMID 33193299, 2020). "More importantly, differentiated Th cells, including Th1, Th2, Th9, and Th17 cells, generated from the naïve CD4+ T cells of OT-II mice were transferred to B16-OVA tumor-bearing mice." (PMID 32508847, 2020). "CIBERSORT analysis revealed significant difference in 16 out of 22 tumor-infiltrating immune cells, especially an enrichment of CD4+ and CD8+ T cells in C2, as well as an enrichment of M2 macrophages in C3." (PMID 33680932, 2020). "Among these cells, naive B cell, CD4+ memory resting T cells, resting Dendritic cells were significantly lower in tumor group compared with the normal group, While CD8+ T cells, Tregs were significantly higher in tumor group (p<0.01)." (PMID 33173412, 2020). "Interleukin‐4 (IL‐4) secreted by tumor cells and CD4+ T cells polarizes TAMs to an M2 phenotype and enhances tumor cell growth, invasion, and metastasis." (PMID 34766109, 2020). "Recent evidence in the field of cancer immunotherapy has conclusively linked the interaction of tumour antigen specific CD4+ and CD8+ T-cells in the tumour microenvironment with effective tumour rejection." (PMID 32650622, 2020). "As a result, we suspected that the reduction in the number of tumour cells was induced by increasing the number of not only CD11c+ and OX-62+ DCs but CD4+ and CD8+ T cells." (PMID 32541941, 2020). "We found that mice with higher (above average) TME CD4+ T cells survived 20.3 days, compared to 17.6 days in tumours with lower infiltration (p = 0.048)." (PMID 32451467, 2020). "The results reveal that the patient's immune system can overcome small tumors; however, if the tumor is large, adoptive therapy with CD4+T cells can be an alternative to both CD8+T cell therapy and cytokines in some cases." (PMID 32148558, 2020). "Adoptive transfer of G-CSFR−/− CD4+ or CD8+ T cells into the peritumoral region of WT or Rag2−/− mice led to significantly decreased tumor growth compared to T cells of WT mice." (PMID 33042110, 2020). "It is involved in inflammatory responses, in the differentiation of CD4 T lymphocytes, in epithelial-mesenchymal transitions, cell proliferation, and tolerance to tumor antigens." (PMID 33330068, 2020). "In a case study, RT treatment coincided with declines in T cells, B cells, pDCs and NK cells, and a shift of the CD4:CD8 ratio correlated with MRI tumor recurrence offering some hope in the identification of treatment response or prognostic indicators." (PMID 32240177, 2020).
tumor (continued). "Infiltration of B cells, CD4+ T cells, CD8+ T cells, neutrophils and dendritic cells was negatively correlated with risk score, suggesting that there are fewer tumor infiltrates in high risk patients." (PMID 33216733, 2020). "An 8-fold increase of T-bet level, together with a 5.58-fold increase of CD4 level was observed in tumor tissues of siRNA2@HPVP-treated mice, as compared with that of the PBS group." (PMID 32332752, 2020). "Immune cells such as CD8+ and CD4+ T cells have been found occasionally in the tumour microenvironment of AS, but the impact of tumour-infiltrating T cells on survival has been inconsistent." (PMID 33182685, 2020). "By multivariate analysis, only the expansion of highly differentiated CD4 T cells and PD-L1 tumor expression higher than 5% were the only independent factors associated with HPD." (PMID 32244396, 2020). "One manifestation of immunosuppression in cancer is appearance of exhausted T cells (CD4+Texhand CD8+Texh) within tumor tissue and in the systemic circulation." (PMID 31090020, 2020). "Anti‐mouse CLEC9A Abs are as effective as anti‐mouse DEC‐205 Abs at delivering Ags to murine cDC1s in vivo to prime CD8+ T‐cell responses, as well as humoral and CD4+ T‐cell responses, which collectively mediate protective tumor‐specific immunity." (PMID 32547743, 2020). "Webb and coworkers have demonstrated that PD-L1+ cells often occur collectively with CD8+, CD4+, and PD-1+ tumor-infiltrating T cells, CD25+FoxP3+ Tregs, and other TIL populations." (PMID 33062717, 2020). "Flow cytometric analysis of fresh tumour tissues in cohort C confirmed these results; dHGP was associated with higher CD8+ and lower CD4+ T cell subsets, resulting in a higher CD8+/CD4+ ratio." (PMID 32418992, 2020). "RT-qPCR analysis of the expression profile of several genes (encoding pro-inflammatory cytokines as well as CD4, CD8, PD-1, and PD-L1) was examined following therapy administered on days 4, 8, and 12 post-tumor inoculation." (PMID 32775618, 2020). "In-flow cytometric data analysis of the tumor digest revealed significantly increases in the population of CD4+, and CD8a+ cells in the TME, compared to all individual treatment groups at 10 days post-treatment." (PMID 32326142, 2020). "In the tumor, we also see a decrease in the CD4+ population while the CD8+ and DNT subpopulations significantly increased." (PMID 32448803, 2020). "Another study using murine models demonstrated that the expansion of tumor infiltrating follicular CD4+ PD1+ T cells after PD-1 blockade therapy correlated with enhanced CD8 CTL anti-tumor responses and tumor growth control." (PMID 33329566, 2020). "The efficacy of a tumor-specific immune response is influenced by the balance between tumor-infiltrating regulatory T cells (Treg) and tumor infiltrating CD4+ and CD8+ T cells (reviewed in Takeuchi and Nishikawa1)." (PMID 33093155, 2020). "Local immune responses in patients with HCC are restrained by tumor and circulating CD4+/CD25+/FoxP3+ Tregs, which suppress effector CD4+ T-cell activity and proliferation." (PMID 31903159, 2020). "The CD4+ T cells were functionally exhausted and found to express high levels of PD-1 with concomitant increased levels of PD-L1 in tumor-derived MDSCs." (PMID 32182988, 2020). "Treg cells in the tumour microenvironment have been shown to restrain the IL-2-dependent acquisition of cytotoxic functions by CD4+ T cells, impeding anti-tumour immunity." (PMID 32290500, 2020). "Tumor rejection by anti-CTLA-4/1MT therapy was associated with enhanced infiltration of functional CD8+ and CD4+ T-cells in the tumor." (PMID 33072086, 2020). "FOXP3 CD4+ Tregs markedly express the IL-8 receptor CXCR1, in order to respond to tumor-derived IL-8 and migrate in cancer tissue, and CD4+ T cells produce IL-8 themselves." (PMID 32727102, 2020).